CD99 (CD99 molecule (Xg blood group))
Description:
Involved in T-cell adhesion processes and in spontaneous rosette formation with erythrocytes. Plays a role in a late step of leukocyte extravasation helping leukocytes to overcome the endothelial basement membrane. Acts at the same site as, but independently of, PECAM1. Involved in T-cell adhesion processes (By similarity).
Synonyms: MIC2; MIC2X; MIC2Y; HBA71; MSK5X
Tractability: Antibody: its Gene Ontology location is reachable by antibodies, with high confidence; UniProt predicts a signal peptide or a membrane-spanning region. PROTAC: ubiquitination databases record sites on it; its protein half-life has been measured.
Gene: Protein-coding gene on chromosome X (2,690,988 to 2,741,312, forward strand). Ensembl gene ENSG00000002586.
Subcellular location: Membrane
Subcellular location (Human Protein Atlas): Golgi apparatus
Pathways (Reactome):
Hemostasis: Cell surface interactions at the vascular wall
Immune System: Immunoregulatory interactions between a Lymphoid and a non-Lymphoid cell
Gene Ontology:
Molecular function: protein binding
Biological process: homotypic cell-cell adhesion; positive regulation of neutrophil extravasation; T cell extravasation
Cellular component: focal adhesion; cytoplasm; plasma membrane; membrane
Homologues: Orthologues: macaque CD99 (90% identical), chimpanzee CD99 (75% identical), dog CD99 (66% identical), tropical clawed frog cd99 (41% identical), zebrafish cd99 (37% identical). Paralogues in human: CD99L2 (32% identical).
Diseases named in the same sentence as CD99 in open-access papers:
CD99 is named in the same sentence as 205 diseases in open-access papers, as found by Europe PMC text mining. Sharing a sentence is not in itself a finding about the gene and the disease. The quoted sentences say what the papers report.
Ewing sarcoma (174 papers, 2002 to 2026). A small round cell tumor that lacks morphologic, immunohistochemical, and electron microscopic evidence of neuroectodermal differentiation. "The diagnostic criteria for Ewing sarcoma often involve identifying a small round cell morphology with positive membranous expression of CD99 and the presence of a gene fusion between FET and ETS families." (PMID 40861426, 2025). "In pathological conditions, increased CD99 expression has been associated with several malignancies, including Ewing sarcoma (EWS), myeloid malignancies, lymphoblastic lymphoma/leukemia, and malignant glioma." (PMID 40427525, 2025). "We performed immunohistochemical analysis with CD99 that is a cell-surface relevant glycoprotein and a relevant diagnostic marker for Ewing sarcoma, showing diffuse strong membranous expression of CD99." (PMID 37923348, 2024). "CD99 is also used as a diagnostic marker for Ewing's sarcoma and is involved in tumor cell migration." (PMID 36732815, 2023). "CD99+ is used as a diagnostic marker by immunohistochemistry in approximately 95% of Ewing sarcomas." (PMID 36636530, 2022). "CD68 and CD99 can be positive in a subset of the cases presenting a potential diagnostic challenge especially in differentiating from Ewing’s sarcoma." (PMID 36225497, 2022). "Positivity for classical IHC markers, such as CD99 and both numyogenin and nuMyoD1, have long been associated with Ewing sarcoma and rhabdomyosarcoma, respectively." (PMID 34638431, 2021). "One approach to Ewing sarcoma involves silencing the miRNA that drives CD99, a hallmark surface antibody in the disease." (PMID 33916177, 2021). "CD99 is a transmembrane protein highly expressed in Ewing sarcoma that has been widely used as a diagnostic marker to distinguish Ewing sarcoma and other small round blue cell tumors." (PMID 33147457, 2020). "Targeting CD99 by antibody-mediated engagement caused caspase-independent cell death, methuosis, in Ewing sarcoma." (PMID 33147457, 2020). "To explore the potential of ATP1A1, BCL11B, GLG1, and CD99 as prognostic biomarkers, we analyzed the association of their expression levels with outcome in a large cohort of Ewing sarcoma patients (n = 166)." (PMID 29416716, 2018). "Usually Ewing's sarcoma associates an overexpression of the CD99 membrane protein and expression of the friend leukemia virus integration (FLI-1)." (PMID 25922782, 2015). "Cell surface transmembrane protein CD99 encoded by the MIC2 gene is consistently expressed in Ewing’s sarcoma cell lines." (PMID 20924476, 2010). "Isolation of CD99-positive CTCs will help identify the metastatic precursor cells and direct novel diagnostic therapy and prognostic options upon therapeutic monitoring of patients with Ewing sarcoma, for clinical decision-making." (PMID 34063272, 2021). "CD99 is a diagnostic marker for Ewing's Sarcoma (EWS), as it is highly expressed by these tumors." (PMID 31001265, 2019). "Furthermore, CD99 has been presented as a diagnostic marker for Ewing's Sarcoma (EWS), as it is highly expressed by most EWS tumors." (PMID 31001265, 2019). "Therefore, CD99 loss induced in Ewing sarcoma cells prolongs nuclear ERK1/2 phosphorylation, which appears to be crucial for shifting the biological functions of ERK1/2 toward neural development and differentiation." (PMID 29534016, 2018). "However, CD99 has been implicated as playing dual roles in tumors, as an oncogene (glioma, Ewing’s sarcoma, lymphoma/leukemia, melanoma, and breast cancer) or an oncosuppressor (osteosarcoma, Hodgkin’s lymphoma, and cancers of the stomach, pancreas, and bladder), as recently reviewed." (PMID 30845661, 2019). "CD99 dual behavior has been reported to be associated with tumor progression in Ewing sarcoma and acute lymphoblastic leukemia, as tumor suppressor in osteosarcoma, and in Hodgkin’s lymphoma, which may be attributed to differential preponderance of CD99 isoforms." (PMID 30845661, 2019).
Ewing sarcoma (continued). "The therapeutic efficacy of CD99-targeted irinotecan-loaded nanoparticles (NV103) was compared to that of untreated controls in Ewing sarcoma xenograft-bearing mice." (PMID 41542564, 2026). "CD99 is a surface glycoprotein strongly expressed in nearly all Ewing sarcoma cells and only minimally expressed in normal tissues, particularly the liver, kidney, intestine, and hematopoietic progenitors—tissues commonly affected by irinotecan toxicity." (PMID 41542564, 2026). "Immunohistochemistry was positive for vimentin, NKX2.2, CD99, and synaptophysin, confirming the diagnosis of Ewing sarcoma." (PMID 42281714, 2026). "Targeting CD99, a surface antigen that is highly expressed on Ewing sarcoma cells, facilitates tumor localization and enhances the intracellular delivery of drug payloads, contributing to the superior antitumor activity of NV103." (PMID 41542564, 2026). "The findings of this study provide compelling evidence that Ewing sarcoma can be effectively treated with CD99-targeted irinotecan-loaded nanoparticles (NV103)." (PMID 41542564, 2026). "In this context, strong and diffuse membranous immunoreactivity for CD99 observed in Ewing sarcoma is of help, but it is worth noting that rare cases of NECs showing CD99 expression have been described." (PMID 40668487, 2025). "CD99 knockdown in human Ewing sarcoma cell lines reduced their ability to form tumours and bone metastases when xenografted into immunodeficient mice." (PMID 40442778, 2025). "These actions underscore CD99 involvement in maintaining the Ewing sarcoma cell undifferentiated state." (PMID 40442778, 2025). "Inhibiting CD99 with these molecules induces a strong cytotoxic response in Ewing sarcoma cells, decreases motility by reducing ROCK2 expression, and hinders anchorage-independent growth." (PMID 40427525, 2025). "A distinctive Ewing sarcoma feature is high CD99 expression, a membrane protein involved in regulating several biological processes including cell adhesion, migration and apoptosis through the PI3 K/RAS/MAPK signalling pathways." (PMID 40442778, 2025). "Per the WHO diagnosis criteria, the essential diagnosis of Ewing sarcoma is based on a combination of small round cell morphology and CD99 membranous expression, but it is also desirable to detect FET-ETS fusions." (PMID 40255709, 2025). "In Ewing sarcoma (ES), cell surface markers such as CD99, Fli-1, and caveolin-1 are used in diagnostics, while glycosphingolipid ganglioside antigen G (D2) (GD2) can serve as a possible target for anti-GD2 monoclonal antibody therapy." (PMID 40134582, 2025). "Although most Ewing sarcomas are recognised morphologically and by immunohistochemical identification of the surface glycoprotein CD99, molecular genetic confirmation of the Ewing sarcoma translocation is mandated." (PMID 39550489, 2025). "IHC analysis of tumors confirmed the expression of the Ewing sarcoma marker CD99 and significantly lower expression of KDM6A and the proliferation marker Ki-67 in sgKDM6A-derived tumors." (PMID 41085408, 2025). "Histopathology of the specimen showed small round blue cells with a high nuclear-to-cytoplasmic (N/C) ratio, and IHC established the diagnosis of extraosseous Ewing's sarcoma (CD99 positive and FL1-1 positive)." (PMID 40896068, 2025). "The neuroblastoma tumouroids demonstrated diffuse strong nuclear PHOX2B staining, Ewing sarcoma tumouroids showed circumferential membrane staining for CD99, and osteosarcoma tumouroids with nuclear SATB2 staining." (PMID 41034452, 2025). "Ewing sarcomas and CIC::DUX4 sarcomas are both CD99 positive; however, Ewing sarcomas tend to have a more distinct, membranous CD99 staining pattern." (PMID 40599504, 2025). "In studies on Ewing Sarcoma, the activation of CD99 in macrophages was shown to induce the secretion of characteristic chemokines such as IL1β, IL6, TNFα, and markers CD80 and CD86 by M1 macrophages." (PMID 41000385, 2025).
Ewing sarcoma (continued). "Immunohistochemistry (IHC) established the diagnosis of extraosseous Ewing's sarcoma (EES) to be CD99 and NKX2.2 positive." (PMID 40896068, 2025). "Despite the differences in typical age of onset and primary location, both bony and cutaneous Ewing sarcomas share similar histopathological features, including small round blue cells that are positive for CD99 on immunohistochemistry." (PMID 40084340, 2025). "Here we report on the discovery of NOA2, a human monoclonal antibody that targets CD99 and is capable of recruiting and reactivating components of the innate immune system to direct antibody-mediated Ewing sarcoma death." (PMID 38534214, 2024). "CD99 is a glycoprotein that has a high level of expression in cells of the hematopoietic system, as well as in cells of Ewing tumors." (PMID 38223368, 2024). "Intriguingly, our case showed intense and diffuse expression of CD99, a transmembrane cell adhesion protein routinely used for Ewing sarcoma differential diagnoses." (PMID 38339014, 2024). "CD99, showing a distinct membranous staining pattern in Ewing sarcoma, can exhibit diffuse cytoplasmic staining in SCOS." (PMID 38332052, 2024). "Two Ewing sarcomas (cases 9 and 10) showed a strong membranous and cytoplasmic CD99 positivity, while in case 11, the staining pattern was heterogeneous." (PMID 38332052, 2024). "Ewing sarcoma expresses CD99 in 90 % of cases and is differentiated from neuroblastoma by the finding of negative synaptophysin." (PMID 39383765, 2024). "For example, another article reported a case of Ewing sarcoma of the scapula that was positive for CD99, vimentin, and bcl-2." (PMID 39588414, 2024). "Histological analysis confirmed Ewing's sarcoma, with diffuse membranous CD99 expression in over 60% of the cells and weak focal expression of S-100." (PMID 39040728, 2024). "FACS binding of IgG1 isoforms to CD99-positive patient-derived Ewing sarcoma cell lines was performed." (PMID 38534214, 2024). "Staining with desmin can be detected in rhabdomyosarcoma or leiomyosarcoma, while CD99, p40, or pankeratin staining is seen in Ewing sarcoma." (PMID 39420880, 2024). "Combination NOA2 and PILRα blockade in vitro potentially reverses the inhibitory CD99:PILRα pathway linking Ewing sarcoma cells and macrophages, leading to restoration of TNF-α secretion." (PMID 38534214, 2024). "Histopathological examination detected a small blue round cell tumour, which was strongly positive for CD99 by immunohistochemistry, thus suggesting a Ewing Sarcoma (EWS)." (PMID 39421445, 2024). "CD99 is upregulated in several malignancies such as Ewing sarcoma and leukemias, while exhibiting limited expression in normal tissue." (PMID 39007347, 2024). "Time course analysis of differential gene expression in Ewing sarcoma experimental models with inducible expression of EWS::FL1 or CD99." (PMID 39524141, 2024). "•Diagnosis of Ewing sarcoma involves a combination of radiological imaging, histological examination, and immunohistochemical analysis, with CD99 positivity being a key marker." (PMID 39383765, 2024). "While there is a CD99+/CD45− phenotype in Ewing sarcoma, CD45−, CD90+, CD56+, and CD57−/+ phenotypes are most frequently observed in rhabdomyosarcoma." (PMID 39767137, 2024). "In our clinical case, CD99 examination revealed over 60% membrane positivity, supporting the diagnosis of Ewing's sarcoma." (PMID 39040728, 2024). "A very rare case was reported of a recurrent immature ovarian teratoma that progressed into primitive neuroectodermal tumor/extraskeletal Ewing sarcoma (immunohistochemical positivity for CD99 and CD56)." (PMID 40729216, 2024). "Ewing sarcoma is an aggressive tumor characterized by small round cells and diffuse CD99 positivity seen mainly in Caucasian childhood and adolescent demographics." (PMID 39383765, 2024). "MCC can express CD99 similar to small round cell sarcomas such as Ewing sarcoma, but will lack EWSR1 rearrangements." (PMID 39136002, 2024).
Ewing sarcoma (continued). "Pathologically, Ewing sarcoma consists of small round basophilic cells with prominent nuclei marked by expression of surface protein CD99." (PMID 36672331, 2023). "CD99 is also expressed on MPCs derived from healthy tissue versus those from patients with Ewing Sarcoma." (PMID 37357305, 2023). "Together, currently a commonly accepted standard for the diagnosis of Ewing sarcoma includes a consistent histological morphology, staining for CD99, and evidence of EWSR1 rearrangement by fluorescence in situ hybridization, PCR or sequencing." (PMID 36672331, 2023). "It was reported that CD138, MUM-1 and CD56 can also be expressed in malignant melanoma, which can lead to a misdiagnosis of plasmacytoma; moreover, CD99 is expressed not only in Ewing’s sarcoma but also in precursor lymphocytes." (PMID 37182167, 2023). "On the other hand, Ewing sarcoma has a homogeneous population of tiny round cells, robust nuclear expression of NKX2.2, and diffuse membrane expression of CD99, which is compatible with the diagnostic value of these markers, as described in earlier research." (PMID 38234938, 2023). "ONB can be separated from Ewing’ s sarcoma by the presence of an S100 positive sustentacular network in most cases as well as diffuse positivity for neuroendocrine markers and negativity for CD99." (PMID 36452830, 2022). "The tumors express canonical EWSR1-FLI1 target genes and stain for known Ewing sarcoma markers including CD99." (PMID 35285802, 2022). "The pathologists believe that the misdiagnosis of Ewing sarcoma is mainly due to the positive expression of CD99 and CD56 in small round cells." (PMID 35372059, 2022). "Flow cytometry confirmed that more than 99% of PSaRC318 cells express surface CD99, a commonly used marker to identify Ewing sarcoma cells." (PMID 36187937, 2022). "As a result, it is important to be aware of CD99 positivity in SS since it can resemble a small round-cell tumor and be misdiagnosed as Ewing sarcoma with a limited antibody panel." (PMID 35372059, 2022). "CD99 is a cell surface glycoprotein that serves as a sensitive, clinically useful marker for Ewing sarcoma." (PMID 35285802, 2022). "Ewing’s sarcoma family of tumors is characterized by the presence of CD99, a membrane glycoprotein marker that is highly sensitive but not specific." (PMID 36465784, 2022). "Adamantinoma-like Ewing sarcoma (ALES) is a rare variant of ES defined by complex epithelial differentiation, with an expression of pancytokeratin, CD99, p40, and synaptophysin and frequent keratin pearl formation." (PMID 35059992, 2022). "At the protein level, high CD99 expression has been observed in Ewing sarcoma, lymphoblastic lymphoma and malignant glioma whereas liver cancer and pancreatic cancer represent a smaller group with low CD99 expression." (PMID 34611477, 2021). "Although our data suggest a tumour-suppressor-like role for CD99 in cancer progression, other cancers, such as Ewing's sarcoma and glioma, demonstrate oncogene-like activity of CD99." (PMID 34374417, 2021). "Exosomes from CD-99-deprived Ewing sarcoma cells can act as “natural” targeted nanocarriers of chemotherapy." (PMID 33916177, 2021). "For the flow cytometric detection of Ewing sarcoma cells in the peripheral blood of patients, CD99, the MIC2 gene product, which is normally expressed by osteoclasts and leukocytes, has been proposed in conjunction with the absence of CD45 [1602]." (PMID 34910301, 2021). "The tumor had consistent features of Ewing sarcoma based on CD99 positivity and EWSR1 rearrangement, although the histological picture was somewhat unusual in that it showed focal myxoid stroma." (PMID 34749732, 2021). "Primary bone tumors from lymphoma can be differentiated on the basis of histology by their microscopic features for most neoplasms except for small cell osteosarcoma and Ewing’s sarcoma, which has to be excluded by IHC for CD99." (PMID 33627139, 2021).